CD4 (CD4 molecule)
Diseases named in the same sentence as CD4 in open-access papers (continued):
Sharing a sentence is not in itself a finding about the gene and the disease.
COVID-19 (continued). "Mildly affected patients had lower reactive CD4+ T cell frequencies than severely affected COVID-19 patients without dexamethasone treatment." (PMID 36881474, 2023). "Transcripts of helper T cell markers CD4 and CXCR4, which is substantially elevated in patients with severe COVID-19, were both elevated, suggesting that CXCR4 activity may be less in bats compared to humans, or it may have a different role in bats." (PMID 37856551, 2023). "Furthermore, we show that both the CD4+ and CD8+ T cells were more activated in the HIV-infected and HIV-uninfected COVID-19 participants compared to the healthy control group." (PMID 38343437, 2023). "This is consistent with the findings of Yu Bai, which indicate that the number of CD4 and CD8 T cells in the peripheral blood was significantly decreased in COVID-19 patients and that the severe damage during the late stage was immune-related rather than virus-related." (PMID 36911695, 2023). "Analysis of regulatory T cells (Tregs) revealed decrement in percentage of CD4+ FoxP3+ T cells as well as in percentage of CD4+ IL-10 producing T cells (data not shown) in terminal stage of COVID-19." (PMID 37057213, 2023). "Another study on PLWH showed that neither HIV-1 plasma viral load nor CD4+T cell count at the time of diagnosis determined COVID-19 outcomes, despite SARS-CoV-2 and HIV-1 infection-mediated T cell lymphopenia." (PMID 37243203, 2023). "Further CIBERSORT analysis demonstrated that the variations in the immune microenvironment of COVID-19 patients may be correlated with CASP1, CD4, and EIF2AK3." (PMID 37228369, 2023). "Among these 677 CD4 T cell clusters, 474 were exclusive to COVID-19 and not found in healthy donors." (PMID 36670287, 2023). "SARS-CoV-2 spike–reactive B cells, CD4+ T cells and, to a lesser extent, CD8+ T cells have been described in the majority of convalescent COVID-19 patients, including those with mild or asymptomatic infection, with formation of substantial immune memory across convalescent individuals." (PMID 36881474, 2023). "For example, CD4+ and CD8+ T-cell responses were only detectable in a minority of convalescent COVID-19 donors following severe infection when analyzed via FC using intracellular cytokine staining, but the opposite is true when utilizing AIM-FC methods with large pools of overlapping peptides." (PMID 38002748, 2023). "COVID-19 vaccination also induces SARS-CoV-2-specific CD8+ and CD4+ T cell responses, which might confer long-term immune memory against SARS-CoV-2." (PMID 37049424, 2023). "Similarly, Mathew and colleagues (2020) observed that among patients with COVID-19, activation levels of CD8 and CD4 T cells (via HLA-DR and CD38 co-expression) were similar to the antiviral responses that have been observed for other infections." (PMID 36675642, 2023). "Volunteers who achieved NAbs after the second COVID-19 vaccination had lower levels of CD4+/CD8+ T cells than those without NAb titers (p < 0.05)." (PMID 38813035, 2023). "Furthermore, a study discovered that deceased COVID-19 participants had markedly decreased total lymphocytes, CD3+ T cell, CD4+ T cell, CD8+ T cell, and CD19+ B cell counts than COVID-19 patients who survived." (PMID 37377785, 2023). "Our data analysis showed that COVID-19 vaccines, regardless of the vaccine type, induced a significantly higher CD4+ and CD8+ T-cell response after the first and second vaccine dose compared to the baseline point before vaccination." (PMID 37515127, 2023). "The aim of the study was to establish parameters with prognostic significance in severe cases of COVID-19 according to life years, laboratory markers of sepsis and MODS, as well as the number of peripheral CD4+ and CD8+T lymphocytes in 20 consecutively selected critically ill patients." (PMID 37780864, 2023).
COVID-19 (continued). "Neutralizing antibodies have been identified as a correlate of protection; concomitantly, a robust, timely, and coordinated adaptive CD4+ and CD8+ T-cell response may be critical for attenuating the severity of COVID-19." (PMID 37513709, 2023). "Recent evidence suggests that particular lymphocyte subgroups, CD4+ and CD8+ T-cells, may demonstrate greater specificity for COVID-19." (PMID 37893192, 2023). "While CD4 SIP level had no impact on COVID-19 vaccine efficacy in elderly patients, our results unraveled a possible predictive role for CD4 SIPhigh T-cell levels in younger cancer patients." (PMID 37334387, 2023). "HLA-DR expression on CD4+, CD8+, and total T cells was also analyzed in COVID-19 patients." (PMID 38035104, 2023). "Activation of CD4+ and CD8+ T cells and T follicular helper cells was similar in SARS-CoV-2–infected pregnant and nonpregnant women, while antibody-secreting B cells were increased in pregnant women during acute COVID-19." (PMID 37036008, 2023). "In aggregated analysis, Eotaxin-3 and Eotaxin-1 levels decreased in COVID-19 patients; however, in sex-segregated analysis, Eotaxin-3, CCL5, IL-21, and IL6+CD4+ T cell levels were lower in female versus male HCW and this sex difference was maintained in female versus male COVID-19 patients." (PMID 37998327, 2023). "Furthermore, CD4+ and CD8+ can be explored more thoroughly as a screening for disease status and can be an useful and consistent predictor of COVID-19 severity." (PMID 37377785, 2023). "In addition, abundant content of activated both CD4+ and CD8+ T cells is a characteristic of COVID-19 increasingly studied." (PMID 37034572, 2023). "However, severe COVID-19 patients had greater frequencies of CD27+ CD62L+ cells (p=0.02) within the total CD4+ T cell population." (PMID 36817450, 2023). "Therefore, we suspect that the disturbed T cell compartments could play a role in COVID-19 immunopathogenesis, leading to impaired antiviral responses by CD8+ T cells and exacerbated inflammation caused by abnormal B cell-mediated antibody responses by CD4+ T cells." (PMID 37835544, 2023). "While cytotoxic CD4+ T cells have been observed in COVID-19, we can show that this increase is not COVID-19 specific and is also observed in other types of pneumonia." (PMID 37730638, 2023). "Moreover, CD4+ T cell responses show balanced production of IL-10 and inflammatory cytokines in asymptomatic infection suspected to provide anti-viral responses without associated pathology, while in symptomatic COVID-19 patients disease response is more polarized." (PMID 37091818, 2023). "The earliest COVID-19 vaccination recommendation released by the Ministry of Health and The Indonesian Society of Internal Medicine back in 2020 suggested against vaccinating PLHIV with a low CD4 count." (PMID 36851176, 2023). "A better understanding of SARS-CoV-2 T-cell and antibody adaptive responses prompted further investigation, leading to the measurement of SARS-CoV-2 immunity while identifying epitope pools detecting CD4+ in 100% and CD8+ T cells in 70% of convalescent COVID-19 patients." (PMID 37240091, 2023). "Several histopathological analyses of endomyocardial biopsies or autopsies from patients with myocarditis following COVID-19 vaccination have revealed spike proteins and S-RBD in the cardiomyocytes, infiltrating predominantly CD4+ T lymphocytes and macrophages." (PMID 38049441, 2023). "Moreover, CD4+ T cells, co-expressing CCR6 and IL-17A, were detected in lung tissues of patients with COVID-19." (PMID 36012146, 2022). "During COVID-19, T and B cell responses have been tracked in blood samples allowing identification of SARS-CoV-2-specific TH1 CD4+ and CD8+ T cell responses and the presence of SARS-CoV-2-specific neutralizing antibodies in COVID-19 patients and vaccine recipients." (PMID 35237261, 2022). "As noted in some previous studies, we observed the proliferation of CD8+ T cells was not as strong as in CD4+ T cells in COVID-19 patients." (PMID 36106521, 2022).
COVID-19 (continued). "To gain further insight into these issues, we examined the relationship between peripheral blood SARS-CoV-2 IFN-γ-producing CD4+ and CD8+ T-cell responses targeting the Spike (S) and membrane (M) proteins, plasma levels of biomarkers of clinical severity and mortality COVID-19 ICU patients." (PMID 35995830, 2022). "In addition, other pieces of evidence indicated that CD4+ T cells and CD8+ T cells are exhausted in patients with COVID-19 who have reduced expression of IFN-γ and IL-21." (PMID 35655192, 2022). "However, the recovered COVID-19 patients in this study showed an increase in CD3+, CD8+, and CD4+ T cell levels in comparison to the moderate infection and under-medication groups." (PMID 35196808, 2022). "Likewise, Irene Cassaniti and colleagues informed that CD4+ and CD8+ T cells from mild COVID-19 patients produce higher IFN-gamma concentrations than those found in T cells from severe cases in response to viral peptides." (PMID 35860236, 2022). "An increased expression of pro-inflammatory cytokines and chemokines along with a consumption of CD4+ and CD8+ T cells, could result in severe inflammatory responses in COVID-19 patients." (PMID 35453526, 2022). "In addition to CD4, we found that CD8 T cells are also dying in severely-affected COVID-19 patients compared to HDs, particularly memory CD8 T cell subsets, which are the most potent in expressing cytotoxic effector molecules." (PMID 35066575, 2022). "The most dominant reactive T-cells, including CD4+, CD8+, CD4+CD154+CD137+, and CD154+CD137+, detected in mild and recovered COVID-19 patients were specific to SARS-CoV-2 structural proteins (SPs), including ORF3a, spike (S), membrane (M), and nucleocapsid (N)." (PMID 36389664, 2022). "This study did not include participants who received a COVID-19 vaccine, had a history of hospitalization for severe disease or had a low CD4+ T-cell count as most PWH in our community are on an effective ART." (PMID 35330585, 2022). "CD4+ T cells are less activated, while CD8+ T cells are more activated, and lymphocytes show an exhaustion phenotype in COVID-19, which may contribute to the pathogenesis of the infection." (PMID 36359755, 2022). "COVID-19 plasma exosomes induced proinflammatory responses in CD4+ T cells, CD8+ T cells, and CD14+ monocytes but not significantly in regulatory T cells, Th17 T cells, or central memory T cells." (PMID 36526691, 2022). "All people living with HIV should receive a COVID-19 vaccine series, and the three-dose primary series of a mRNA vaccine is recommended for patients with advanced HIV (CD4 < 200 cells/mm3 or <14%) followed by a 4th booster dose at least 3 months after the third dose." (PMID 35456055, 2022). "CD4+ cells did not respond to exosomes obtained from these same COVID-19 patients later in their hospitalization." (PMID 36526691, 2022). "It has already been demonstrated that CD4+ T cells from COVID-19 patients do not show alterations in the frequency of naïve and effector/central memory populations, and our data confirmed these results (not shown)." (PMID 36012246, 2022). "The cell-cell communication analysis revealed a CD22-CD45 signaling between the Class-switched memory B cell and the Activated CD4+ T cells, in healthy but not in the COVID-19 positive or recovered." (PMID 36532041, 2022). "CD4/CD8 ratio is a prognostic factor for the severity of COVID-19, reflecting the negative impact on prognosis of those individuals whose immune response has abnormal CD8+ T-cell expansion during the early response to the infection." (PMID 35814752, 2022). "The protein-protein interaction-level network obtained from the differentially expressed genes revealed elevated TNF-α signaling in the Activated CD4+ T cells, IL-6 signaling in the CD8+ TEM cells, which are indicative of elevated inflammatory response during active COVID-19." (PMID 36532041, 2022).
COVID-19 (continued). "IL-2 is majorly produced by CD4+ and CD8+ T cells, as well as some B cells and dendritic cells; its important function is to foster the proliferation of CD4+ and CD8+ T cells Few recent studies have reported that higher levels of IL-2 was seen in asymptomatic and mild COVID-19 groups." (PMID 35336918, 2022). "The innate immune response (such as increased neutrophils, pro-inflammatory macrophages, and lymphopenia) and adaptive immune responses (activation of CD4+ T cells and CD8+ T cells) play important roles in autoimmunity or anti-inflammation of COVID-19 patients." (PMID 35387441, 2022). "We found that CD4+ cells from severe convalescent patients had significantly higher capacity to produce TNF-α, IL-2 and CD107a at time-point I, compared to healthy controls and mild/moderate COVID-19 convalescents." (PMID 35757700, 2022). "CD4+ T cells were decreased in moderate/severe COVID-19 HD patients and in severe COVID-19 non-HD patients." (PMID 35265078, 2022). "Decreased CD3+CD4+CD45RO−CD62L+ and CD3+CD8+CD45RO−CD62L+ T cell frequencies and increased CD3+CD8+CD45RO−CD62L− cell counts were found to indicate a poor outcome in patients with acute COVID-19." (PMID 35337053, 2022). "Eventually, the CD4+/CD8+ ratio (for Th and Tc cells, respectively), CD19+ (B cells), CD3+CD4+ (Th cells), CD3+CD8+ (suppressor T lymphocytes), and CD16+56+ (NK cells) may affect COVID-19 severity." (PMID 36423150, 2022). "HIV-infected patients on ART with a moderately low recently recorded CD4 count (<350 cells/μL) attending an HIV clinic in an informal setting outside Cape Town, South Africa, were recruited to this study after the first COVID-19 wave and during the second and beginning of the third wave." (PMID 35746693, 2022). "In response to polyclonal stimuli, basal production of interleukin-2 (IL-2) and interferon (IFN-) gamma significantly decreased, and the programmed cell death protein 1 (PD-1) increased in CD4+ and CD8+ T cells from participants who posteriorly developed severe COVID-19 compared to mild cases." (PMID 35860236, 2022). "In this study, we also showed that CD3+ T cells, CD4+ T cells, and CD8+ T cells were significantly reduced in patients with COVID-19 with T2DM, suggesting that these patients had significant dysregulation in lymphocyte, leading to impaired function of cellular immune and decreased viral clearance." (PMID 37359706, 2022). "The elevated IL-10 levels in NK cells as well as CD4+ and CD8+ T cells of severe patients might be also considered as a protective response against the harmful effect of cytokine storm seen in COVID-19." (PMID 36110850, 2022). "The reduction in T cells, mainly CD4+ and CD8+, is common between severe COVID-19 cases." (PMID 35196808, 2022). "From an immunological point of view, the authors highlighted that, similarly to patients with sarcoidosis, BALF cell count analysis of hospitalized patients with COVID-19 showed accumulation of CD4+ and CD8+ T cells and CD4/CD8 ratio often higher than 1.5; blood lymphocytopenia was also detected." (PMID 36148452, 2022). "This differential helminth-induced immunomodulation of CD4+ and CD8+ T cells might also be relevant to the immunogenicity of current COVID-19 vaccines in endemic helminth regions." (PMID 35764965, 2022). "CD8 T cells, CD4 T cells, and B cells significantly differed between COVID-19 patients and controls: CD8 and CD4 T cells were significantly lower (FDR p < 0.05), and B cells were significantly higher (FDR p < 0.05) in COVID-19 patients compared to controls." (PMID 36371196, 2022). "Among CD4+ T cells, there was a predominant Th2 and Th17 response with increased gene expression of GATA3 and RORG transcription factors, more prominent in severe COVID-19 and SARS-CoV-2 antibody-producing patients." (PMID 35962159, 2022).
COVID-19 (continued). "It is of interest to note that patients who recover from COVID-19 have SARS-CoV-2 specific CD8+ and CD4+ T cells 82, supporting the fact that, the SARS-CoV-2 virus may have mechanisms that evade the efficient innate immune response." (PMID 36313221, 2022). "High expression of CD69 on CD4+ and CD8+T cells in COVID-19 leads to over-activation of NK cells and T cells, which may cause over-activation of the immune response." (PMID 36420258, 2022). "Increased ratio of CD4+ TEMRA cells in moderate and severe COVID-19 was previously reported." (PMID 35464396, 2022). "In a study on 65 KTR patients, a lack of response to COVID-19 vaccines was associated with African American race, being on high-dose anti-metabolite therapy, and having lower pre-vaccination CD3, CD4 T-cell, and serum IgM levels." (PMID 36422345, 2022). "Among the 10 and 12 putative SARS-CoV-2-specific and expanded groups, we further chose those that include clones from ≥3 different COVID-19 patients with ≥55% clones having more than one cell, resulting in five and two groups for CD8+ and CD4+ T cells, respectively." (PMID 35064122, 2022). "Although high-affinity class II-restricted T cells specifically recognizing the M protein have not been identified, it is stably recognized by CD4+ T cells in some COVID-19 cases." (PMID 36389144, 2022). "However, the expression of type II IFN receptors was higher in COVID-19 patients in both the cell types, whereas type I IFN receptors were upregulated in the CD4+ central memory T cells of the recovered individuals." (PMID 36532041, 2022). "Furthermore, in our study on a similar cohort of patients, both COVID-19 positive and COVID-19 naïve groups had similar levels of H1N1 influenza virus-specific CD4+ and CD8+ memory T cells, suggesting the longevity of influenza-induced cellular responses." (PMID 36146622, 2022). "In addition to Tfh cells, Th1 CD4+ T cells secreting Th1-type cytokines such as IFN-γ, TNF, and IL-2 can also be detected in patients with COVID-19." (PMID 35891267, 2022). "Here we propose that ROS and Arginase produced by M-MDSC are the mediators of CoV2 antigen-specific T cell suppression.Increasing evidence suggest that both CD4 and CD8 T cell responses are important for COVID-19 outcome and maintenance of CoV2 immunity, even in the absence of humoral response." (PMID 35812392, 2022). "Representative dot-plots exemplify the contrast of CD3+CD4+ T cells simultaneously expressing IL-2, IFN-gamma, and PD-1 in whole blood samples exposed to polyclonal molecules from participants who experienced mild or severe COVID-19 throughout the follow-up." (PMID 35860236, 2022). "As predicted, in most of the COVID-19 patients, SARS-CoV-2–activated CD4+ and CD8+ T cells could be detected." (PMID 36447270, 2022). "In addition, we also found that CD4+ T cells and CD8+ T cells in COVID-19 critical cases showed greater reductions than those in severe patients." (PMID 36403042, 2022). "Children with MIS-C, however, displayed reduced CD4+ T cell responses, with 43% exhibiting FC > 2 to SARS-CoV-2 spike MP and only 25% to the non-spike MP (P = 0.0004 and P = 0.003 compared with convalescent COVID-19, respectively)." (PMID 35044955, 2022). ", using flow cytometry, discovered that COVID-19 patients had greater levels of CD95 than controls, and that increased CD95 expression in CD4+ cells was related with decreased CD4+ counts, revealing a further mechanism for lymphopenia by which CD95 triggered apoptosis in COVID-19 patients." (PMID 36590587, 2022). "Lymphopenia is associated with COVID-19 disease severity and the depletion of CD8+ T cells, but not CD4+ T cells, and is associated with poor prognosis of COVID-19 patients." (PMID 36685601, 2022). "There is a positive correlation between the probability of contracting COVID-19 and age, and a negative correlation with CD4+ T-cell count and being vaccinated." (PMID 35340627, 2022).